TNF (tumor necrosis factor)
Diseases named in the same sentence as TNF in open-access papers (continued):
Sharing a sentence is not in itself a finding about the gene and the disease.
cancer (continued). "Low H2O2 levels can trigger NF-κB, an oxidative stress detector; this can trigger the production of anti-apoptotic genes and pro-cancer cytokines like interleukin-6 (IL-6) and tumor necrosis factor alpha (TNF-α) and may activate or suppress MAPK phosphorylation." (PMID 40732979, 2025). "Also, TNFα blockade may affect the balance between pro-apoptotic and anti-apoptotic signals in cells, potentially allowing cancer cells to proliferate." (PMID 40282506, 2025). "Cancer treatments may trigger persistent inflammation, resembling inflammaging observed in older populations, marked by elevated levels of cytokines including tumor necrosis factor-alpha (TNF-α), interleukin (IL)-1α, IL-2, IL-8, and IL-12p70." (PMID 40838185, 2025). "However, p38 MAPK activation in prostate cancer protects cancer cells from TNF-α-induced apoptosis." (PMID 41450917, 2025). "In addition, immune cell– secreted TNF‐α may also induce cancer cells to produce ROS that further trigger tumor‐promoting cascades." (PMID 40377005, 2025). "In this regard, inflamed visceral adipose tissue becomes a source of TNF-α, which induces pro-angiogenic factor overexpression as well as upregulation of anti-apoptotic factors, such as cyclin D1, cyclin E, and Bcl-2, that contribute to cancer cells’ survival and migration." (PMID 40227577, 2025). "Additionally, cancer cachexia is associated with decreases in serum albumin, triglycerides (TG), cholesterol, high-density lipoprotein (HDL), and low-density lipoprotein (LDL) and increases in pro-inflammatory cytokines such as IL-6, IL-1β, and TNF-α." (PMID 40469669, 2025). "Thus, TNF-α exhibits a “double-edged sword” effect in the cancer microenvironment." (PMID 41450917, 2025). "The relatively brief mean follow-up duration of approximately 1 year implies that the long-term ramifications of TNF - α antagonist exposure on cancer risk might not be comprehensively apprehended." (PMID 39980561, 2025). "Regular PA stimulates the release of skeletal muscle-derived IL-6, which inhibits the release of pro-inflammatory factors (TNF-α and IL-1β) and promotes the release of the anti-inflammatory factor IL-10, inducing an anti-inflammatory environment and improving health outcomes in cancer survivors." (PMID 39896788, 2025). "Furthermore, our findings are consistent with registry-based studies from Western countries, which similarly reported no increased cancer risk with long-term TNF inhibitor use in patients with AS." (PMID 41302997, 2025). "In addition to altering major metabolic pathways, our gene set enrichment analysis showed that other cancer‐related pathways, including the general apoptosis pathway and inflammation pathways such as INFα response, TNFα response, and INFγ response, are affected after CAMK2D knockout." (PMID 39840457, 2025). "Treatment may necessitate systemic therapy, and although biologics such as tumor necrosis factor alpha inhibitors are contraindicated in patients with cancer, interleukin 17 inhibitors (eg, secukinumab) may offer a promising treatment strategy for these patients." (PMID 39936159, 2025). "Conversely, downregulation of NF-κB and TNF signaling pathways —typically involved in malignancy suppression during early carcinogenesis —may diminish cellular defenses against tumorigenesis, thereby exacerbating cancer progression." (PMID 40361356, 2025). "Inflammatory cytokines, particularly tumor necrosis factor-alpha (TNF-α), interleukin (IL)-6, and interferon-γ (IFN-γ), are major drivers of many symptoms of the disease and are thought to be responsible for the metabolic changes associated with tissue loss in cancer wasting." (PMID 40430444, 2025).
cancer (continued). "Despite the fact that acute TNF-α blockade might present a short-term beneficial effect on anti-PD-1-related CVAEs, long-term TNF-α inhibition is implicated with CD8 + -T-cell senescence and toxicity which might lead to a possible cancer relapse." (PMID 38520533, 2025). "When comparing the upregulated differentially expressed genes of carcinoma cells between control and compressed B16 cells, we observed enrichment in pathways including cytosolic DNA‐sensing pathway, together with chemokine, NF‐κB, TNF, and TGF‐β signaling pathways." (PMID 39737867, 2025). "Therefore, we examined whether TNFα either enhanced the sensitivity of cells to chemotherapeutics or increased cancer immunogenicity to promote antitumor immunity." (PMID 38195677, 2024). "However, the association between TNF-α inhibitors and cancer has not been replicated in other studies." (PMID 39046819, 2024). "An increase in the general risk of cancer was also not observed with TNF-α inhibition." (PMID 39046819, 2024). "Similarly, inhibitors targeting the activator of transcription (STAT), JAK/signal transducer, IL‐1, IL‐6, and tumor necrosis factor (TNF) are effective, alone or in synergy with senescence‐inducing chemotherapy, to effectively abrogate the proliferation and migration of cancer cells." (PMID 38660685, 2024). "Accumulation of NRF2 in cancer cells may activate expression of inhibitory cytokines and ligands directly by transcriptional regulation or by activating inflammation pathways such as interferon pathways, TGFβ pathway, TNFα pathway, and complement pathway." (PMID 38241355, 2024). "The most significantly enriched pathways of HSPcluster-B are associated with cancer and inflammatory responses, including type II interferon to JAK-STAT signaling pathway, IL10 family to JAK-STAT signaling pathway, EGF EGFR PI3K NFKB signaling pathway, and TNF NFKB signaling pathway." (PMID 39430254, 2024). "Moreover BCL3 has been implicated in TNF-alpha mediated signaling via stabilisation of RIP1 through CYLD ubiquitination in non-cancer cells suggesting that it may also have a role in TNF-alpha responses in the local microenvironment." (PMID 38195591, 2024). "Thus, we speculate that TNF-α may also contribute to the PARPi killing effect in GSDMC-positive cancer cells." (PMID 37883181, 2024). "The PSOLAR registry indicated that long-term exposure to anti-TNFα treatments might increase cancer risk (OR 1.54), but this increase was not statistically significant when analyzed by individual anti-TNFα agents." (PMID 38610706, 2024). "Studies have shown significant reductions in inflammatory markers such as C-reactive protein (CRP), tumor necrosis factor-alpha (TNF-α), and interleukin-6 (IL-6) among individuals adhering to the MD, suggesting its pivotal role in mitigating chronic inflammation-associated with cancer development." (PMID 38773621, 2024). "Notably, the cancer-promoting chronic inflammation which contributes oncogenic transformation, underscores a need to decipher the DR pathway and design agents that will block TNF/TRAIL/DR pro-survival signaling." (PMID 38698424, 2024). "Furthermore, TNF has been shown to contribute to cancer immune evasion." (PMID 39034318, 2024). "Moreover, we observed an increased expression of TNFα in ZWPro‐treated cancer cells." (PMID 39231370, 2024). "In addition, the DEGs were enriched in pathways related to inflammation, cancer, aging, apoptosis, and several signaling pathways such as the IL-17 signaling pathway, TNF-alpha signaling pathway, NF-kappa B signaling pathway, MAPK signaling pathway, and NOD-like receptor signaling pathway." (PMID 39540047, 2024). "However, other IAP antagonists, particularly those with confirmed biosafety in clinical trials, could also be used as long as their concentration in vivo can reach the threshold that kills cancer cells in combination with TNFα." (PMID 39105847, 2024). "In addition, higher TNF-α and IL-6 expression was observed in the Cat D KO cancer cells." (PMID 38297161, 2024).
cancer (continued). "Thus, IL-6 and TNF-α are being investigated in clinical trials for pancreatic and other cancers." (PMID 38390872, 2024). "Interestingly, drugs targeting pro-inflammatory molecules such as anti-TNF-α and anti-IL-1β are emerging as highly promising options for pain control and could potentially be employed in managing cancer pain." (PMID 38433844, 2024). "Toll-like receptor signaling may be involved in the production of TNF-α in cancer." (PMID 39830670, 2024). "Furthermore, TNFα does play important functions in immunosurveillance for cancer cells." (PMID 38730981, 2024). "Moreover, the top hallmark signatures enriched in genes highly expressed in sensitive cancer lines were identical with the ones found in TAKi sensitive GSCs, including Interferon Alpha/Gamma Response, TNFα signaling via NF-κB, and Epithelial Mesenchymal Transition." (PMID 38632238, 2024). "Conflicting reports of whether TNFα-induced RELA translocation is cell cycle regulated may be due to cancer cell type-specific deregulation of cell cycle proteins or RELA may not physically interact with E2F1 in PDAC cells in general or specifically in unsynchronised cells." (PMID 39110005, 2024). "The relationship between inflammation and muscle density has been reported in non-cancer populations, and attempts to define the mechanistic pathways suggest that cytokines such as TNF, IL-6, and IL-1β may stimulate proteolysis and inhibit anabolism, leading to muscle breakdown and wasting." (PMID 38512880, 2024). "Therefore, the anti-cancer activity of SMs is closely correlated to TNF signaling." (PMID 39578442, 2024). "Moreover, our findings on the modulation of metastatic markers such as uPAR, uPA, CXCR4, MT1-MMP, and TNF-α by PEDF, Dox, and their combinations add critical insights into the molecular mechanisms underlying cancer progression and confirmed the results from migration." (PMID 38474001, 2024). "Our study revealed that elevated serum IL-6, TNF-α, and TGF-β and decreased IL-10 levels revealed that patients with ESCC and model mice demonstrated increased immune levels, and these inflammatory cytokines are considered important mediators associated with inflammation and cancer." (PMID 38834834, 2024). "Ultimately, we show that our protocol might be employed to identify perturbations in methylation marks upon extracellular stimuli in eukaryotic cells such as TNF-α, paving the way for its use in studying a cell- or condition-specific (for example, healthy versus cancer) analysis of RNA methylation." (PMID 39594581, 2024). "When we looked for a predictive correlation with ORR, only baseline levels of TNF-α, a cancer-promoting and immunosuppressive cytokine, reached statistical significance in responder females, confirming a worse antitumor immunity in presence of high baseline TNF-α levels as already described." (PMID 38443899, 2024). "TNF was also detected in cancer and might lead to a poor prognosis of cancer." (PMID 36945884, 2023). "The up-regulation of TNF-α may prime cancer cells towards apoptosis." (PMID 37162544, 2023). "TNF-α is a multifunctional cytokine that participates in the regulation of immune–inflammatory reactions involved in host defense against infectious, autoimmune, and endocrine diseases and cancer, and its actions help determine the survival or death of various cells." (PMID 36985596, 2023). "Moreover, patients with RA who experienced a diagnosis of cancer during treatment with anti-TNFα have not shown a worse prognosis of the underlying cancer." (PMID 36672491, 2023). "Thus, TNF-α is considered to be an effective anti-cancer cytokine." (PMID 38001420, 2023). "Overcoming the resistance of cancer cells to TNFα may have a potential therapeutic benefit." (PMID 36900285, 2023). "TNF-α signaling may play a paradoxical role in cancer development and antitumor immunity." (PMID 38186567, 2023).
cancer (continued). "In a multivariable Cox model, after adjusting for confounders, there was no increase in the risk for new or recurrent cancer after vedolizumab (HR 1.38; 95% CI 0.38–1.36) or anti-TNF (HR 1.03; 95% CI 0.65–1.64) therapy compared to foregoing the use of an immunomodulator." (PMID 36831424, 2023). "On the other side, TNF could act as a cancer inhibitor/killer." (PMID 37298889, 2023). "In addition, TNF has been confirmed to confer cancer cell stemness properties." (PMID 37534250, 2023). "Also, TNFα is able to induce EMT in several cancer entities, including HNSCC." (PMID 37685940, 2023). "Consequently, employing TNF as a cancer drug was largely abandoned." (PMID 36195672, 2023). "There were 27 subsequent cancers (18 new and 9 recurrence) in the control group with an incidence rate of 2.4 per 100 p-y and only 1 recurrent cancer in patients under biologics, in particular, anti-TNFα, with incident rates for cancer per 100 p-y of 0.4 for VDZ, 1.8 for USK, and 0.7 for anti-TNFα." (PMID 36672491, 2023). "In addition, miRNAs differentiating particular cancer grades were identified followed by prediction which of them may regulate the activity of selected genes involved in TNF-α signaling." (PMID 37233761, 2023). "Interestingly, we find that the inflammatory cytokine TNFα simultaneously induces stemness and senescence signaling activation in colonic epithelial cells, and such seemingly paradoxical pathway activation can be a selective pressure for cancer development." (PMID 37845228, 2023). "Nevertheless, in addition to pulmonary and metabolic diseases, the multiple roles of TNF-α in an array of pathophysiologies, including cancer, neurological diseases, and cardiovascular diseases, which might influence the predictive value of TNF-α in SO, cannot be ignored." (PMID 37853348, 2023). "Hence, linoelaidic acid-induced TNF-α may promote the nitrite generation in MCF-7 that played a crucial role in cancer cell growth arrest." (PMID 37644076, 2023). "In addition, the identified highly-voted functional modules in most cancer types encompassed a wide range of biological processes, including regulation of tumor necrosis factor production, cellular response to cytokine stimulus, adaptive immunity, anti-apoptosis, cell migration, and angiogenesis." (PMID 37475016, 2023). "In addition, no increased risk of cancer with anti-TNF therapy after an index cancer diagnosis has been demonstrated, suggesting lengthy post-cancer drug holidays are unlikely to be necessary." (PMID 37674502, 2023). "Moreover, it was reported that the HMGB1 released by cancer cells undergoing ferroptosis could increase the tumor necrosis factor α (TNFα) of macrophages." (PMID 36926345, 2023). "In some forms of cancers, anorexia and cachexia may be attributed partly to the release of TNF-α." (PMID 37383489, 2023). "Furthermore, recent studies indicate that TNF-α and IL-6 promote cancer cachexia in different types of cancer, including gastric and CRC, by protein 16 containing PR domain (PRDM16) gene overexpression via the STAT3 signaling pathway, which induces the browning of WAT." (PMID 37760840, 2023). "Therefore, we hypothesized that interactions between EBV‐infected NPC cells (expressing LMP1) and stromal cells (producing TNFα) would lead to synergistic formation of invadopodia by the cancer cells." (PMID 36420735, 2023). "The association between TNF antagonists and cancer incidence was examined in several trials; despite variations in endpoint definitions, duration of exposure, and indications, no appreciably elevated risk of cancer was found." (PMID 38139369, 2023). "Similarly, TNFα showed differential expression among different cancers through a bar plot." (PMID 37892820, 2023).
cancer (continued). "According to many different studies, these components, when extracted and used in a specific way, may intervene in processes that are vital in carcinogenesis such as cancer cell proliferation, modifying the ability of those cells to infiltrate other tissues and stimulating tumor necrosis factor." (PMID 37608943, 2023). "Furthermore, anti-cancer activity includes induction of pro-apoptotic factors such as TNF-α, suppression of tumor growth by blocking TGF-β, invasion, metastasis, cell cycle arrest, modulation of gene activity, ROS production, and reduction of cancer stemness in vitro and in vivo." (PMID 37446385, 2023). "In addition, NSAIDs effectively inhibited the TNF-α-induced upregulation of cancer cell migration." (PMID 36765695, 2023). "However, the study provided only an association between anti-TNF therapy and cancer outcome, not the effects of continuing anti-TNF therapy after the diagnosis of cancer." (PMID 36983432, 2023). "The selective inactivation of TNFR1 receptor by XPro1595 should thus result in a better safety profile, avoiding potential neurological problems and limiting drug-induced increased susceptibility to infections and cancer that are characteristics side effects of the non-selective TNF inhibitors." (PMID 37332353, 2023). "We identified several mechanistic pathways and gene ontology biological processes like TNF signalling pathway, signal transduction, cholesterol metabolic process and cellular response to cytokine stimulus which provide a clear view of the genotypic link among multiple cancers and FI." (PMID 36608061, 2023). "However, as more recent data are collected, they show that risk for recurrent and new cancer in patients with IBD is not increased by thiopurines or anti-TNFα agents, and possibly not even by new biologics such as VDZ and UST." (PMID 37370740, 2023). "Therefore, our research may contribute to the understanding of the role of TNF in cancer progression and antitumor immune responses, providing important insights for more effective immunotherapeutic strategies." (PMID 37153654, 2023). "In the multivariate analysis, neither anti-TNFα nor anti-TNFα + IMM therapy was associated with increased risk of cancer recurrence or new cancer development (HR 1.03, 95% CI 0.65–1.64 and HR 1.22; 95% CI 0.75–1.99, respectively) compared to patients without any immunosuppressant therapy." (PMID 36672491, 2023). "Our RNA-seq data showed that Tagln overexpression can alter several inflammatory pathways, including the NF-κB and TNF signaling pathways, indicating that Tagln may participate in the crosstalk between cancer cells and CAFs by mediating the inflammatory process in the TME." (PMID 36990991, 2023). "TANs provide a favorable environment for cancer development, angiogenesis and metastatic spread by secreting cytokines and chemokines, such as interleukin-2 (IL-2), interleukin-6 (IL-6), interleukin-10 (IL-10), tumor necrosis factor α (TNF-α) and vascular endothelial growth factor (VEGF)." (PMID 36661728, 2023). "Finally, we show that Pol III inhibition impinges on NF-κB activity, which may potentially explain the sensitisation of cancer cells to TNFα." (PMID 36900285, 2023). "Recognition of these cognate cancer‐specific antigens by the engineered antibodies causes to initiation of some signaling pathways in T cells that induce production of several pro‐inflammatory cytokines (IFN‐γ, TNF‐α, IL‐6, and IL‐2) and cytolysis (osmotic lysis) of cancer cells." (PMID 36583504, 2023). "Indeed, accumulative data suggest that the risk of recurrent and new cancer in patients with a history of cancer is not increased by thiopurines and anti-TNF agents." (PMID 36831424, 2023). "Moreover, the increased targeting of cancer cells by macrophages chemically modified with aptamers was also associated with an increased expression of MHC class I and II molecules and release of proinflammatory cytokines (TNFα and IL12)." (PMID 36854896, 2023).